IGF1R (insulin like growth factor 1 receptor)
Diseases named in the same sentence as IGF1R in open-access papers (continued):
Sharing a sentence is not in itself a finding about the gene and the disease.
Hyperinsulinemia (84 papers, 2009 to 2026). An increased concentration of insulin in the blood. "Collectively, we provide evidence of dysregulation of aging-associated renal IGF1R/AKT after perinatal obesity that might be related to hyperinsulinemia, supporting the notion of premature aging processes." (PMID 36768831, 2023). "In the context of previously published studies, these results suggest that Black women may be more susceptible to the cancer promoting effects of hyperinsulinemia, due to higher levels of circulating insulin and higher ratio of tumor IR/IGF-1R expression." (PMID 32393319, 2020). "However, during development of DM, IGF-1R was found overexpressed or activated in other organs and tissues in response to hyperglycemia and hyperinsulinemia, thereby causing deterioration of DM." (PMID 31847392, 2019). "For example, while hyperinsulinemia consistently decreased IGF1R protein levels in mouse primary cultures, Igf1r mRNA remained unchanged." (PMID 40105689, 2025). "Firstly, IR results in hyperinsulinemia, which promotes cancer development by increasing the uptake of glucose in cancer cells and interacting with the insulin-like growth factor-1 receptor." (PMID 41007166, 2025). "Hyperinsulinemia with downstream IGF-1/IGF-1R signaling activates the PI3K–AKT–mTOR and MAPK pathways, supporting the survival and clonal expansion of mutated thyrocytes in the context of chronic low-grade inflammation." (PMID 41514562, 2025). "T2DM and obesity are states of hyperinsulinemia, and insulin is known to directly activate IGF1-R on epidermal cells and increase IGF1 levels in the blood, which is the proposed mechanism of action of AN in hyperinsulinemic states." (PMID 39165464, 2024). "Later on, another study from Japan revealed EGCG attenuates obesity-related hepatocarcinogenesis though suppressing the IGF/IGF-1R axis, alleviating hyperinsulinemia, and reducing chronic inflammation." (PMID 37292151, 2023). "Preclinical in vivo rodent studies have demonstrated that hyperinsulinemia can activate not only its cognate IR but can also bind to and hence stimulate the insulin-like growth factor 1 receptor (IGF1R)." (PMID 35244142, 2022). "Pre-clinical studies have shown that IR can drive and accelerate breast tumor progression independently of IGF-1R in the hyperinsulinemia mouse model." (PMID 33429867, 2021). "The tumor promoting effects of hyperinsulinemia were ameliorated by either lowering circulating insulin levels with a β3-adrenergic agonist, or with inhibitors of the IR/IGF-1R, PI3K, and/or mTOR." (PMID 33604295, 2020). "Hyperinsulinemia significantly increases reflux-related esophageal cancer incidence, possibly through enhancing IGF1R/p-ERK1/2 pro-proliferation signaling in esophageal cells." (PMID 29662006, 2018). "We used the hyperinsulinemic non-obese FVB/N (Friend leukemia virus B strain) MKR (muscle (M)-IGF1R-lysine (K)-arginine (R) mouse model to evaluate the exclusive role of hyperinsulinemia in the pathogenesis of EAC related to duodeno-esophageal reflux." (PMID 29662006, 2018). "Accordingly, it is possible that hyperinsulinemia in the db/db-Min/+ mice activates the signaling cascades involving the IGF-1R, resulting in a proliferative response." (PMID 22174655, 2011). "Based on the ChIP-seq data, the same FOXO1 feedback loop influencing Igf1r, Insr, Irs1, and Irs2 may be present in other tissues experiencing hyperinsulinemia conditions." (PMID 40105689, 2025). "Finally, metabolic stress in the form of hyperinsulinemia promoted cellular IGF1 resistance via downregulation of Igf1r mRNA and protein, through a phosphoinositide 3-kinase/forkhead box O1 (PI3K-FOXO1)-mediated transcriptional mechanism." (PMID 40105689, 2025). "Importantly, this study uncovered that hyperinsulinemia induces IGF1 resistance in hypothalamic neurons by downregulating IGF1R and IRS2 through the PI3K-FOXO1 signaling pathway." (PMID 40105689, 2025).
Hyperinsulinemia (continued). "Overall, we describe the regulation of IGF1 signal modulators and highlight the anorexigenic role of IGF1 in the ARC hypothalamus, and we provided evidence that hyperinsulinemia induces cellular IGF1 resistance through reduced IGF1R levels in a PI3K-FOXO1–dependent manner." (PMID 40105689, 2025). "Our results may also explain why hyperinsulinemia is a risk factor for BPH; high insulin levels can crossactivate the IGF1R." (PMID 37971878, 2024). "The upregulation of IGF1R and HER2 in hyperinsulinemia could also increase the likelihood of forming IGF1R/HER2 heterodimers, which support cell growth, proliferation, and progression in esophageal carcinogenesis." (PMID 38136271, 2023). "Interestingly, lipodystrophic Bscl2−/− mice develop cardiac hypertrophy due to increased basal IGF1 receptor (IGF1R)‐mediated PI3K/AKT signalling secondary to hyperinsulinemia." (PMID 35384404, 2022). "Moreover, it is noted that hyperinsulinemia can contribute to the growth and metastatic spread of BC via activation of the insulin receptor/insulin-like growth factor 1 receptor (IGF-1R) signaling pathways." (PMID 36046117, 2021). "Interestingly, mice exhibiting a β-cell–specific deletion of the insulin receptor (IR) or insulin growth factor 1 receptor (IGF1R) are glucose-intolerant and show fasting hyperinsulinemia." (PMID 32934005, 2020). "Tumors from the MKR mice, relative to wild-type mice, had increased levels of phosphorylated IR but not IGF-1R, thereby identifying the activation of the IR as a major contributor to hyperinsulinemia-associated tumor growth." (PMID 33604295, 2020). "Given the significant reduction of talin-1 reported in the present study, this finding could be related to the previously reported alterations in lamellar IGF-1R during hyperinsulinemia." (PMID 32596266, 2020). "In conclusion, hyperinsulinemia in DM activates IGF1-R and triggers downstream target effectors." (PMID 31847392, 2019). "The compensatory hyperinsulinemia may overstimulate the mitogenic pathway and promote cell proliferation via IR-A or IGF-1R." (PMID 31354621, 2019). "The fact that hyperinsulinemia is a pathological hallmark of type 2 diabetes, along with the structural and functional homology between INSR and IGF1R, prompted us to further investigate the potential roles of insulin and INSR in PCa development and progression." (PMID 24434591, 2014). "Both IGF-1 and IGF-1R tend to have stronger mitogenic and antiapoptotic effects, and the hyperinsulinemia that occurs in insulin-resistant individuals may enhance this effect." (PMID 21773024, 2011). "Deletion of IGF-1R caused hyperinsulinemia and glucose intolerance without changing β cell mass." (PMID 38811543, 2024). "Thus, the interplay among hyperinsulinemia, insulin receptor resistance, downregulation of insulin-like growth factor-1 receptor, and IR signaling pathways could explain the molecular basis of the brain IR state." (PMID 37891752, 2023). "However, IR inhibitor also results in several side effects, such as hyperinsulinemia caused by IGF1R mAb, which targets both IGF1R and IR without selectivity." (PMID 33429867, 2021). "Therefore, targeting IGF-1R pathway, reversal of hyperinsulinemia and IGF by dietry recommendations or metformin may decrease resistance of EGFR-TKI as well as reduce the risk of cancer recurrence in tumor patients." (PMID 25048361, 2014). "Hyperinsulinemia induced IGF1 resistance, accompanied by reduced IGF1R protein, as well as Igf1r and Irs2 mRNA expression via over-activation of phosphoinositide 3-kinase/forkhead box O1 (PI3K-FOXO1) signaling." (PMID 40105689, 2025). "We found that hyperinsulinemia promoted hypothalamic neuronal IGF1 resistance, evidenced by reduced INSR and IGF1R protein levels in immortalized hypothalamic neurons, primary hypothalamic cultures, and human iPSC-derived hypothalamic neurons." (PMID 40105689, 2025). "Thus, inhibiting IGF-1R while controlling hyperinsulinemia may be an effective cancer therapy." (PMID 34611148, 2021).
Hyperinsulinemia (continued). "In the animal model, several studies carried out in hyperinsulinemic male mice overexpressing a dominant-negative, kinase-dead IGF-1R in muscle (MKR mice), have supported the important role of chronic hyperinsulinemia in cancer progression." (PMID 29184536, 2017). "Hyperinsulinemia leads to increased production of insulin-like growth factor-1 (IGF-1), which activates insulin-like growth factor-1 receptor (IGF-1R)." (PMID 25048361, 2014). "In fact, hyperinsulinemia not only directly engages insulin and IGF-1R but also amplifies mitogenic signalling by boosting free IGF-1 availability, which activates IGF-1R, initiating signalling cascades such as PI3K, inhibiting apoptosis, and promoting protein synthesis." (PMID 40806650, 2025). "LY294002, but not PD 0325901, blocked insulin-mediated repression of Igf1r and Irs2, further demonstrating that hyperinsulinemia reduces Igf1r through PI3K signaling." (PMID 40105689, 2025). "Our data suggest the involvement of IGF1R in esophageal carcinogenesis, even in the absence of hyperinsulinemia or obesity conditions." (PMID 34684639, 2021). "Chronic sustained hyperinsulinemia, INSRs, IGF1Rs, and INSR/IGF1R hybrids, in addition to chronic inflammation, ncRNAs, and microbiota have been proposed as factors that may play a role in all tumor stages." (PMID 34681797, 2021). "Hyperinsulinemia-induced IGF1R and HER2 up-regulation could also increase the possibility of forming of IGF1R/HER2 heterodimers to support cell growth/proliferation/progression in esophageal carcinogenesis." (PMID 29662006, 2018). "Yet, hyperinsulinemia by increasing the bioavailability of IGF-1 and IGF-2 may favor tumor progression and the activation of IGF-1R, IR/IGF-1R hybrids, IR-A, and their interaction with other molecular partners." (PMID 30513575, 2018). "A direct anabolic of effect of hyperinsulinemia on the skeleton and independent of BMI has been previously reported, and this effect is probably mediated through the osteoblast-specific insulin-like growth factor 1 receptor." (PMID 28719612, 2017). "Here, we show that mice with IR and IGF1R-specific dual inhibition induced by OSI-906 at 45 mg/kg daily for 7 days developed lipodystrophy, steatosis, and β cell proliferation accompanied by hyperglycemic-hyperinsulinemia and hyperlipidemia." (PMID 28646158, 2017). "Chronic hyperinsulinemia suppresses hepatic synthesis of insulin-like growth factor binding proteins, thereby increasing free Insulin-like Growth Factor-1 (IGF-1) bioavailability, which subsequently activates IGF-1 receptors (IGF-1R) to promote cellular proliferation and metastatic potential." (PMID 41561157, 2025). "Notably, hyperinsulinemia may increase the growth of orthotopic mammary tumors through direct stimulation of the IR and without the involvement of the IGF-1R." (PMID 29184536, 2017). "Additionally, in malignant neoplasms, hyperinsulinemia may potentiate the proliferative effect of IGF-2, which is overexpressed in 90% of adrenocortical carcinomas, through the binding of insulin receptor A (IR-A), IGF-1 receptor (IGF-1R) and hybrid receptor IR-A/IGF-1R." (PMID 39199391, 2024).
breast tumors (74 papers, 2006 to 2026). "Taken together, these findings indicate that reduced IGF1R in breast tumors is associated with alterations in intrinsic tumor epithelial cell pathways as well as extrinsic immune microenvironment signatures that promote metastasis." (PMID 36568144, 2022). "Any insulin use was significantly associated with higher expression of IGF1R (OR = 2.36; 95%CI:1.02–5.52; p = 0.04) and p-mTOR (OR = 2.35; 95%CI:1.13–4.88; p = 0.02) in breast tumors." (PMID 29486734, 2018). "This provides a rationale for the combined targeting of p110α with IGF1R or p110β in patients with breast tumors harboring PIK3CA mutations." (PMID 27048245, 2016). "In another study investigating IGF1R levels in breast tumors, there were significantly higher levels of IGF1R in tumors from BRCA1 mutation carriers as compared with noncarriers." (PMID 19843326, 2009). "Moreover, this group reported that cytoplasmic WWP1 expression was highly expressed in breast tumor tissues and was linked to estrogen receptor alpha (ERα) and insulin-like growth factor receptor 1 (IGF-1R) expression in breast carcinoma." (PMID 34226507, 2021). "To substantiate these findings, we then studied the association of IGF-1R expression (by immunohistochemistry (IHC) in 440 breast tumor specimen) with ERα/Src and ERα/PI3K expression, two markers already shown to be strongly correlated with nongenomic mERα signaling in a previous study." (PMID 30692633, 2019). "To investigate molecular events associated with the loss of IGF-1R function in breast tumor cells, we inhibited IGF-1R in human cell lines using an IGF-1R blocking antibody and analyzed MMTV-Wnt1-mediated mouse tumors with reduced IGF-1R function through expression of a dominant-negative transgene." (PMID 30458886, 2018). "Coherent with the failure of mutant BRCA1 to suppress IGF1R gene transcription, immunohistochemical analyses of primary breast tumors derived from a cohort of 185delAG BRCA1 mutation carrier patients revealed almost twofold higher IGF1R levels than in sporadic breast tumors." (PMID 28706506, 2017). "It was reported that BRCA1 deficient breast tumors have higher IGF-1R expression." (PMID 26510816, 2015). "Consistent with the postulate that mutant BRCA1 may lead to deregulated IGF1R expression, a recent immunohistochemical analysis revealed significantly elevated IGF1R levels in primary breast tumors derived from BRCA1 mutation carriers, compared to sporadic tumors." (PMID 24904527, 2014). "It has been reported that the IGF-1R pathway plays an important role in gynecologic cancers such as breast tumors." (PMID 40768543, 2025). "To test this, we chose the following oncogenes: H-RASV12G, H-RAS61L, and IGF1-R; around 50% of breast tumors express activated IGF1-R." (PMID 38803515, 2024). "A study of 438 breast tumours found that IR was expressed in 49% of breast tumours compared to 32% for IGF1R." (PMID 36920947, 2023). "Together, these observations suggest that paracrine signaling between breast tumors and surrounding tissue, in which stromal-produced IGF ligands stimulate IGF-1R on tumor cells, is essential for secondary breast tumor expansion." (PMID 36556357, 2022). "There is now evidence that the IGF1R also has tumor or metastasis suppressive functions; IGF1R expression in breast tumors correlates with positive overall patient survival and a more differentiated tumor phenotype." (PMID 36568144, 2022). "For example, IGF-1R was frequently overexpressed in breast tumors, and its overexpression was important in the malignant transformation of mammary cells." (PMID 36233084, 2022). "These analyses revealed that lymph node positivity is ~20% higher in human breast tumors with low IGF1R expression versus those with high IGF1R expression." (PMID 36568144, 2022).
breast tumors (continued). "In agreement with the inability of mutant BRCA1 to suppress IGF1R transcription, primary breast tumors derived from BRCA1 mutation carrier patients expressed significantly higher levels of IGF1R than sporadic breast tumors." (PMID 35432218, 2022). "These expression analyses of human breast tumors with low IGF1R were performed with genes we identified as dysregulated in our mouse tumor model with reduced IGF1R signaling." (PMID 36568144, 2022). "In these studies, breast tumors expressing a dnIGF-1R that colonize the bone display reduced mitosis and increased apoptosis compared to tumors expressing functional IGF-1R." (PMID 36556357, 2022). "The IGF-1/IGF-1R pathway has a prominent oncogenic role in breast tumors, where it triggers direct autocrine proliferative and migratory actions on epithelial cancer cells." (PMID 33557316, 2021). "Altogether, these findings suggest that the IGF-1/IGF-1R axis primes the breast tumor microenvironment toward the acquisition of an angiogenic phenotype through the S100A7/RAGE signaling." (PMID 33557316, 2021). "At least 50% of breast tumors present with activated IGF-1R and the level of circulating IGF-1 positively correlates with the incidence of estrogen receptor positive (ER positive) breast tumors." (PMID 32435229, 2020). "To achieve this, we analyzed the IGF-1R/ERα interaction in breast tumors by bright field PLA, in which the presence of protein interactions is visualized as brown dots." (PMID 30692633, 2019). "Boxplot representation of Wnt2 (A) (Student’s t test, P < 2.2 × 10− 16) and Fzd9 (Frizzled9) (B) (Student’s t test, P < 2.2 × 10− 16) in human breast tumors with low (IGF-1R z-score < − 1) versus high (IGF-1R z score > 1) IGF-1R expression." (PMID 30458886, 2018). "Further analysis revealed IL-6, CCL2, and MMP9 were upregulated in breast tumors with low compared to high IGF-1R." (PMID 30458886, 2018). "Recent queries of the Cancer Genome Atlas (TCGA) database for IGF-1R expression identified higher IGF-1R expression in luminal A and luminal B breast tumors and lower expression in HER2-like and triple-negative tumors." (PMID 30458886, 2018). "We observed an association between insulin treatment and increased p-mTOR and IGF1R expression of breast tumors, especially in premenopausal women." (PMID 29486734, 2018). "Boxplot representation of MMP2 and CHOP (E, G) expression in human breast tumors with low (IGF-1R z-score < − 1) versus high (IGF-1R z-score > 1) IGF-1R expression (Student’s t test, MMP2, P < 6.864 × 10− 10; CHOP, P < 3.172 × 10− 10)." (PMID 30458886, 2018). "The percentages of positive expression for p-ER, EGFR, p-ERK1/2, p-mTOR and IGF1R were also in line with previous published data, using similar population selection, IHC methods, and assessment criteria in primary invasive breast tumors." (PMID 29486734, 2018). "Immunohistochemical analysis of primary breast tumors indicated that high levels of IGF1R correlated with ipsilateral tumor recurrence following lumpectomy and radiation therapy." (PMID 27446805, 2016). "On the other hand and given the well-documented involvement of INSR in various types of cancer, in particular breast tumors, experts in the field advise the combined targeting of both IGF1R and INSR." (PMID 27446805, 2016). "In a panel comparing other potential imaging targets (EGFR, HER2, GLUT1 and others), IGF-1R was found to be suitable for molecular imaging strategies in 80% of female and 77% of male breast tumors." (PMID 25743390, 2015). "Up to 50% of breast tumors express the activated form of the type 1 insulin-like growth factor receptor (IGF1R)." (PMID 25964777, 2015). "Immunohistochemical studies of invasive breast tumor tissues showed that nearly 42% of TNBC patient samples expressed markedly high active IGF1R/IR levels, which was suggested to be indicative of poor survival." (PMID 25749031, 2015).